TRPC1 (transient receptor potential cation channel subfamily C member 1)
Diseases named in the same sentence as TRPC1 in open-access papers (continued):
Sharing a sentence is not in itself a finding about the gene and the disease.
atherosclerosis (10 papers, 2014 to 2025). A disease characterized by the build-up of fatty material and calcium deposition in the arterial wall resulting in partial or complete occlusion of the arterial lumen. "Accumulating evidence indicates that up‐regulated TRPC1 expression is associated with increased cell proliferation and the pathogenesis of various vascular diseases, including atherosclerosis, pulmonary hypertension and restenosis, as well as lung cancer." (PMID 36562293, 2023). "TRPC1 expression in atheroma macrophages was associated with advanced atherosclerosis, whereas medial TRPC6 upregulation correlated with increased histamine-induced calcium transients and coronary contractility." (PMID 28756533, 2017). "TRPC6 expression and histamine-induced active tension as well as TRPC1 expression and atherosclerosis associations were analyzed." (PMID 28756533, 2017). "Further research is required to elucidate the signaling pathways and molecular mechanisms involved in TRPC1-mediated atherosclerosis." (PMID 37588590, 2023). "The mechanisms by which TRPC1 channels regulate macrophage function in atherosclerosis are not fully understood." (PMID 37588590, 2023). "In addition, The inhibition of neointimal hyperplasia by a TRPC1 specific antibody (T1E3) further supports the involvement of TRPC1 in the pathogenesis of vascular obstructive diseases, such as atherosclerosis." (PMID 40078961, 2025). "In VSMCs, TRPC1-based SOCs mediate Ca2+ entry pathways which contribute to contractility, proliferation, and migration, and are potential therapeutic targets for cardiovascular diseases such as hypertension and atherosclerosis." (PMID 28301277, 2017). "The future effort is required to investigate whether selective TRPC1/TRPC3 channel blockers can be clinically used for treating atherosclerosis in patients with high ox-LDL." (PMID 27472391, 2016). "Therefore, we speculate that spironolactone may slow down atherosclerosis progression by reducing TRPC1-positive monocyte adhesion to the coronary endothelium and their subsequent extravasation." (PMID 28756533, 2017). "Selective expression of TRPC1-based SOCs and Orai1-based CRAC channels in distinct VSMC phenotypes may provide useful strategies for developing therapeutic strategies to treat distinct progression phases of cardiovascular diseases such as hypertension and atherosclerosis." (PMID 28301277, 2017).
colorectal cancer (10 papers, 2021 to 2024). A primary or metastatic malignant neoplasm that affects the colon or rectum. "The same was found in some colorectal cancer cell lines, where it was proposed that TRPC1 regulated the PI3K/CaM/AKT axis independently of Ca2+." (PMID 35887266, 2022). "The expression of TRPC1 has been shown to be dysregulated in several types of cancer and was recently shown to be correlated with poor prognosis in colorectal cancer." (PMID 35887266, 2022). "For instance, the high expression of TRPC1 correlated with low overall and event-free survival in colorectal cancer patients and disease-free survival in lung cancer patients." (PMID 35887266, 2022). "As a result, colorectal cancer cells expressing TRPC1 proliferate, migrate, invade and metastasize significantly more than cells with TRPC1 knockdown." (PMID 36158191, 2022). "For instance, one study identifies that TRPC1 overexpression promotes tumor growth and metastasis in human colorectal cancer cells." (PMID 35754147, 2022). "Overexpression of TRPC1 promoted the proliferation, invasion, and migration of colorectal cancer cells." (PMID 34642309, 2021). "In this study, we systematically uncovered the oncogenic role of TRPC1 on colorectal cancer cell functions and tumorigenicity in both primary CRC mice using Trpc1 knockout (Trpc1-/-) and nude mice xenografted with gain or loss of TRPC1 human CRC cells." (PMID 34642309, 2021). "In summary, our findings provided evidence that TRPC1 upregulation is a common event in colorectal cancer and an altered expression of TRPC1 is important for the genesis, tumor growth, and metastasis of CRC." (PMID 34642309, 2021). "TRPC1 overexpression is also correlated with colorectal cancer progression and poor prognosis." (PMID 36158191, 2022). "Likewise, TRPC1 is overexpressed and links with unsatisfying clinicopathological characteristics or poor prognosis in patients with colorectal cancer and gastric cancer." (PMID 35106847, 2022). "Here, CaM, a multifunctional intracellular Ca2+-binding protein, works as a connecting protein between TRPC1 and PI3K, thereby regulating colorectal cancer progression." (PMID 35887266, 2022). "Our data show that TRPC1 activates the PI3K/AKT pathway by upregulating the protein expression levels of p-AKT and p-PI3K in adipocytes, a phenomenon similar to that observed in colorectal cancer cells, human atrial myocytes, and diabetic rats." (PMID 39631563, 2024). "As TRPC1 can potentially regulate MAPK signaling cascades through KRAS in liver and colorectal cancer cells lines, it would be interesting to further investigate the interplay between TRPC1, KRAS, and the metabolic changes implicated in the acidification of the tumor microenvironment of PDAC." (PMID 36230869, 2022). "Additionally, immunofluorescence assay showed that, besides cytomembrane, TRPC1 also located in the cytoplasm of colorectal cancer cell lines HT29, SW620, and HCT116, which highlighted the possible role of TRPC1 as the cytoplasmic protein in CRC cells." (PMID 34642309, 2021). "As one of the seven mammalian members of the TPRCs, TRPC1 plays a pivotal role in colorectal tumorigenesis and tumor progression by activating the calmodulin-mediated PI3K/AKT signaling axis and may be a novel target for colorectal cancer treatment." (PMID 36389709, 2022). "Thus, targeting TRPC1 might be a novel strategy for hindering uncontrolled growth and metastasis in PI3K/AKT-addicted colorectal cancer." (PMID 34642309, 2021).
lung carcinoma (10 papers, 2013 to 2024). "The expression of TRPC1, 3, 4, 6 in lung cancer has been detected and the association of TRPC3 expression with the prognosis of lung adenocarcinoma has been described." (PMID 23840757, 2013). "Such a scenario has also been reported for other cancer cell models, for instance, in A549 lung cancer cells, where the KD of TRPC1 decreased the protein expression of Cyclin D1 and D3, leading to an increased number of cells in the G1 phase." (PMID 35887266, 2022). "Another study discloses that TRPC1 is up‐regulated in carcinoma tissue compared with para‐carcinoma tissue in non‐small cell lung cancer patients." (PMID 35754147, 2022). "TRPC1 is an important Ca2+ regulator in a variety of cell types including malignant gliomas, ovarian cancer, and lung cancer." (PMID 27183905, 2016). "The expression of TRPC1, 3, 4 and 6 channels was significantly lower in the poorly differentiated lung cancer than in the well-moderately differentiated group." (PMID 23840757, 2013). "Accordingly, the deregulated expression of TRPC1 correlates with breast, pancreas and lung cancers." (PMID 39594815, 2024). "The mRNAs of TRPC1, 3, 4 and 6 were detected in both normal lung and lung cancer tissues." (PMID 23840757, 2013). "Linear multivariance regression analysis also showed a negative correlation of the mRNA expression of TRPC1, TRPC3, TRPC4 and TRPC6 to lung cancer differentiation grade with standardized β coefficient sequence of TRPC1 (−0.563)>TRPC4 (−0.360) >TRPC6 (+0.271) and TRPC3 (−0.057), respectively." (PMID 23840757, 2013). "Using isoform-specific blocking antibodies, we found that the blockade of TRPC1, TRPC4 and TRPC6 channels causes a significant inhibition of A549 cell proliferation, suggesting that TRPC1, TRPC4 and TRPC6 are important for lung cancer cell proliferation." (PMID 23840757, 2013). "In this study, we have shown that TRPC1, TRPC3, TRPC4 and TRPC6 exist in human lung cancer including the adenocarcinoma, squamous cell carcinoma and the adenocarcinoma-derived cell line A549." (PMID 23840757, 2013). "Another study also recognizes that up‐regulated TRPC1 is correlated with poor DFS, but is not linked with OS in non‐small cell lung cancer patients." (PMID 35754147, 2022). "In conclusion, we found that TRPC1, TRPC3, TRPC4 and TRPC6 channels are expressed in lung cancer." (PMID 23840757, 2013). "On the contrary, over-expression of TRPC1 and TRPC6 increased the A549 proliferation, however the effect of overexpression of TRPC3 and TRPC4 has not achieved significance in the lung cancer cells." (PMID 23840757, 2013).
Obesity (10 papers, 2017 to 2026). Accumulation of substantial excess body fat. "This study constructed mouse models with endothelial cell-specific TRPC1 deficiency and overexpression to investigate their roles in obesity-related metabolic disorders." (PMID 40568618, 2025). "To further elucidate the role of endothelial TRPC1 deficiency in the pathogenesis of obesity, we systematically evaluated the glucose and lipid metabolic profiles in TRPC1EC−/− and TRPC1fl/fl mice under both basal and obese conditions." (PMID 40568618, 2025). "Gain-of-function experiments confirm that the overexpression of endothelial TRPC1 significantly ameliorates obesity-associated phenotypes in mice." (PMID 40568618, 2025). "Conversely, endothelial TRPC1 overexpression significantly ameliorates obesity-associated metabolic dysfunction, as evidenced by reduced visceral fat deposition, enhanced insulin sensitivity, and restored thermogenic capacity in adipose tissue." (PMID 40568618, 2025). "TRPC1 inhibits the positive effect of exercise on type 2 diabetes risk under a HDF-induced obesity environment and plays an important role in the regulation of adiposity via autophagy and apoptosis." (PMID 41009007, 2025). "Specifically, the deficiency of endothelial TRPC1 exacerbates metabolic dysfunction associated with obesity, whereas its overexpression exerts significant protective effects." (PMID 40568618, 2025). "Studies have demonstrated that TRPC1, which serves as a crucial store-operated calcium entry channel in AT, plays an important role in revealing the mechanisms underlying obesity and obese asthma." (PMID 38365763, 2024). "The mechanism by which TRPC1 KO mice fed a HF diet and exercised are protected from obesity and type II diabetes risk needs further investigation." (PMID 29074621, 2017). "This study is the first to show that TRPC1 KO mice that exercise are protected from HF diet-induced obesity and type II diabetes risk because of decreased adipose tissue mass and adipocyte number as a result of reduced autophagy and increased apoptosis." (PMID 29074621, 2017). "The data thus far show that TRPC1 is the major Ca2+ entry channel in adipocytes and that loss of TRPC1 decreases obesity risk in HF fed mice that exercise." (PMID 29074621, 2017). "Importantly, endothelial-specific TRPC1 overexpression reverses metabolic dysfunction associated with obesity." (PMID 40568618, 2025). "Overall, these findings suggest that TRPC1 plays an important role in the regulation of adiposity via autophagy and apoptosis and that TRPC1 inhibits the positive effect of exercise on type II diabetes risk under a HF diet-induced obesity environment." (PMID 29074621, 2017). "Building on the critical role of TRPC1 in cardiovascular homeostasis and the pathogenesis of obesity, this study investigates its functional mechanisms in endothelial metabolic regulation." (PMID 40568618, 2025). "Collectively, these findings indicate that endothelial TRPC1 overexpression ameliorates obesity-induced metabolic dysfunction." (PMID 40568618, 2025). "Evaluation of the metabolic protective effects of TRPC1 overexpression in HFD-induced obesity models revealed that TRPC1ECKI/KI mice exhibited significant attenuation of weight gain following 12 weeks of HFD intervention." (PMID 40568618, 2025). "In vivo, transgenic miceexpressing porcine TRPC1 (Tg-pTRPC1) on a HFD were used as obesity models to explore the potential effect of TRPC1 on fat deposition, hepatic steatosis, glucose metabolism, and insulin sensitivity." (PMID 39631563, 2024). "In vivo, transgenic mice expressing porcine TRPC1 exhibited aggravated high-fat diet–induced obesity, hepatic steatosis, and insulin resistance." (PMID 39631563, 2024). "Our research reveals that TRPC1 is critical for adipogenesis and can improve animal meat quality and the treatment of human obesity." (PMID 39631563, 2024).
Obesity (continued). "Recently it was shown that TRPC1 inhibited exercise-induced protection against obesity produced by a high-fat diet and in type 2 diabetes." (PMID 38885005, 2024). "Taken together, these results suggest that TRPC1 is essential for adipocyte differentiation and adipokine secretion, which regulate metabolic homeostasis to reduce obesity." (PMID 31182642, 2019). "Overall, our results provide evidence that TRPC1 not only plays a key role in adipocyte differentiation, but is essential for adipokine secretion, and dysfunction in these vital processes leads to obesity and metabolic syndrome." (PMID 31182642, 2019). "The present study investigated the involvement of TRPC1 in diet-induced obesity and type II diabetes." (PMID 29074621, 2017). "Among the TRP family, certain members, such as transient receptor potential canonical 1 (TRPC1), transient receptor potential canonical 6 (TRPC6), and transient receptor potential melastatin 2 (TRPM2), have been implicated in obesity, oxidative stress, and kidney diseases." (PMID 41009007, 2025). "We established the Tg-pTRPC1 model to investigate the relationship between TRPC1 and obesity." (PMID 39631563, 2024). "The role of TRPC1 in adiposity and obesity-associated metabolic diseases has not yet been determined." (PMID 29074621, 2017). "Although the transient receptor potential canonical 1 (TRPC1) channel demonstrates tissue-specific heterogeneity in metabolic regulation, its functional role within endothelial cells and its contribution to metabolic disturbances associated with obesity remain unresolved." (PMID 40568618, 2025). "Collectively, these findings indicate that endothelial TRPC1 deficiency does not alter the development of HFD-induced obesity; however, it may contribute to metabolic regulation through non-significantly reduced energy expenditure." (PMID 40568618, 2025). "However, the exact role of TRPC1 in adipose tissue mass changes, development of obesity, and obesity-associated metabolic disease risks has not yet been determined." (PMID 29074621, 2017). "We established endothelial-specific TRPC1 knockout (TRPC1EC−/−) and overexpression (TRPC1ECKI/KI) mouse models, which were integrated with a high-fat diet (HFD)-induced obesity paradigm." (PMID 40568618, 2025). "To investigate the metabolic regulatory functions of endothelial TRPC1 under both physiological and obese conditions, we employed a high-fat diet (HFD)-induced obesity model." (PMID 40568618, 2025). "Endothelial TRPC1 deficiency, while not altering the severity of HFD-induced obesity, significantly exacerbates impaired glucose tolerance, insulin resistance, and dyslipidemia." (PMID 40568618, 2025). "To better understand TRPC1 function in vivo, we subjected the mice to a HFD to induce obesity." (PMID 39631563, 2024). "Moreover, experimental evidence indicates that several TRP channels play an important role in the onset of diabetes (5, –, 7) or diet-induced obesity; however, the role of TRPC1 in these circumstances is not yet established." (PMID 29074621, 2017).
ovarian carcinoma (10 papers, 2013 to 2024). A malignant neoplasm originating from the surface ovarian epithelium. "For instance, TRPC1 expression is significantly decreased in cisplatin-resistant (A2780 and SKOV3) and carboplatin-resistant (A2780) ovarian cancer cell lines, suggesting that the reduced expression of TRPC1 is linked to chemoresistance." (PMID 32575381, 2020). "One study using the SKOV3 ovarian cancer cell line showed the involvement of TRPC1 in cisplatin resistance." (PMID 36142596, 2022). "On the other hand, in high histopathological grade ovarian cancer, TRPC1 expression was negatively correlated with chemoresistance." (PMID 35141145, 2021). "Several studies have been developed in order to assess the contribution of TRPC1, however, little is known about its role in cell proliferation, tumorigenesis, and drug resistance in ovarian cancer." (PMID 32785177, 2020). "TRPC1 protein is aberrantly expressed in a variety of human cancers, including nasopharyngeal carcinoma, ovarian carcinoma, and non-small lung cell cancer." (PMID 24603752, 2014). "Indeed, cisplatin-resistant SKOV3 ovarian cancer cells showed a significant decrease in TRPC1 mRNA levels, compared to sensitive cells." (PMID 36142596, 2022). "The interactions of TRPC1 with numerous proteins/genes, chemicals, biological processes, and mRNA, all involved in the regulation of ovarian cancer drug resistance and related to cell growth and death as well as gene expression, indicate a role for TRPC1 in drug resistance in ovarian cancer." (PMID 32785177, 2020). "For example, TRPC1, TRPC3 and TRPC6 were proven to be participated in proliferation of multiple types of cancer, including breast caner, ovarian cancer, liver cancer, and brain cancer." (PMID 29463225, 2018). "The two TRPC1 bands in the gel were α and β isoforms, and the bands for TRPC4 were α, β, γ and δ isoforms, respectively, as we described in ovarian cancer cells." (PMID 23840757, 2013). "Moreover, the alternative spliced variants may also contribute to the functionality of TRPC channels, such as TRPC1 and TRPC4 spliced isoforms in ovarian cancer SKOV3 cells." (PMID 23840757, 2013).
Hypertension (9 papers, 2014 to 2025). The presence of chronic increased pressure in the systemic arterial system. "Recently, it was concluded that the TRPC1 gene regulates body metabolism and that, except for hypertension, phenotypes of mice after deletion of the TRPC1 gene resembled mice with metabolic syndrome." (PMID 41009007, 2025). "The studies conducted on these channels indicated that TRPM4, TRPC1, TRPC3, and TRPC6 channels play an important role in the creation and progression of hypertrophy and hypertension." (PMID 32641948, 2019). "This indicates a general effect on the systemic vasculature due to the simultaneous deletion of TRPC1, 3 and 6 rather than the occurrence of systemic hypertension or an effect due to hypoxia." (PMID 36569761, 2022).